LEP (leptin)
Diseases named in the same sentence as LEP in open-access papers (continued):
Sharing a sentence is not in itself a finding about the gene and the disease.
infection (continued). "In malnourished individuals with extremely low BMI, a dramatic reduction in leptin levels was observed, which was associated with thymic atrophy, reduced T-cell function, and increased susceptibility to infection." (PMID 32655492, 2020). "Both low systemic leptin or leptin-deficiency and impaired leptin signaling conditions are associated with increased susceptibility to infections." (PMID 32824322, 2020). "It has been suggested that an increased risk of infection is associated with reduced levels of leptin, e.g., in malnourished individuals." (PMID 31878238, 2019). "Malnutrition predisposes children to infection and the nutritional hormone leptin is important in the immunity to the enteric pathogen Entamoeba histolytica." (PMID 30112008, 2018). "A few such infections; bacteria, virus and fungus, and parasite infections and their pathogenicity in either low systemic leptin or leptin-deficiency and impaired leptin signaling conditions are presented below in detail." (PMID 29868503, 2018). "The leptin-deficient (ob/ob) and LepRb-deficient (db/db) mice were highly susceptible to infection with E. histolytica, whereas wild-type C57BL/6 mice were resistant." (PMID 30534129, 2018). "For example, leptin-deficient (Ob/Ob) or leptin receptor–deficient (db/db) mice showed impaired ability to clear or control infection by Klebsiella pneumoniae, Listeria monocytogenes, and Mycobacterium tuberculosis." (PMID 27114296, 2016). "Control of infection by leptin treatment is associated with an induction of NO in splenocytes along with higher IgG2a Ab in plasma of L. donovani-infected normal mice." (PMID 27114296, 2016). "Leptin plays a role in both innate and adaptive immunity and leptin deficiency causes immune dysfunction and increased risk of infection in mice and man." (PMID 25098352, 2015). "On the contrary, the treatment with leptin exclusively at the intracerebral level, improved the survival, and the risk of infection of these mice, again suggesting the importance of the central leptin signaling in the modulation of immune functions." (PMID 24778633, 2014). "Immune driven I-cell hyperplasia and resultant weight loss leads to a reduction in the inflammatory adipokine leptin, which in turn heightens protective immunity during infection." (PMID 23349631, 2013). "From an immunological point of view, leptin-deficient mice (ob/ob) display reduced cellularity in the spleen and thymus, and show increased susceptibility to infection." (PMID 21695035, 2011). "It has been shown that conditions of reduced leptin production are associated with increased infection susceptibility." (PMID 20368778, 2010). "Leptin deficiency is linked to heightened vulnerability to various infections." (PMID 40095902, 2025). "Our findings reveal for the first time that IFNβ plays a crucial role in the innate immune response and is linked to the leptin pathway, paving the way for further research into the relationship between these metabolic signaling pathways and the cellular response to infection." (PMID 40125513, 2025). "Albeit the association found between leptin levels and infection susceptibility may be speculative, it is supported by a large cohort, robust results and a large amount of experimental evidence." (PMID 37217748, 2023). "Additionally, it has been reported to contribute to infection by diminishing immune responses, causing chronic inflammation, elevating leptin levels, provoking abnormal blood glucose levels, and stimulating the secretion of inflammatory hormones and cytokines." (PMID 35409556, 2022). "The elevated leptin levels in the obese mice play a causal role in the severity of infection." (PMID 35406000, 2022). "However, the value of leptin for predicting healthcare-associated infections (HAIs) in older inpatients remains to be determined." (PMID 35011102, 2022).
infection (continued). "Moreover, starvation produces a significant decrease in leptin levels, associated in turn with infection, as a result of a dysfunctional immune response, and reversed by exogenous administration of leptin." (PMID 36457996, 2022). "However, the effect of the leptin mutation on the response to infection is very specific for a particular gene signature set and is not a general effect on all inflammatory genes." (PMID 35933481, 2022). "However, a decrease in leptin levels (such as in undernourished individuals) can lead to a risk of infection." (PMID 35027962, 2021). "This review explores potential interactions between infectious agents and insulin and leptin signaling pathways, and discuss possible mechanisms underlying the relationship between infection, metabolic dysregulation, and brain disorders, particularly focusing on the roles of insulin and leptin." (PMID 34795562, 2021). "Parasite infections are reported to cause damage to intestinal mucosal epithelial cells by inducing the activation of mesenteric lymph nodes and perturbations in the adjacent adipose tissue to secrete leptin." (PMID 32824322, 2020). "The link between leptin and susceptibility to infection has been studied in animal models." (PMID 33584724, 2020). "Leptin is a major regulator of appetite, energy homeostasis, metabolism, and may also influence the immune response, for example, a decrease in leptin levels is associated with an increase in infection susceptibility." (PMID 30836628, 2019). "Furthermore, intact leptin signaling plays a key role in offering protection against gut parasite infections e.g., E. Histolytica caused amoebiasis." (PMID 29868503, 2018). "Generally, leptin-deficiency is associated with enhanced susceptibility to several infections." (PMID 29868503, 2018). "Leptin deficiency is associated with impaired cell-mediated immunity and increased susceptibility to infection, and neutrophil chemotaxis is a key component of inflammation and host response to infection." (PMID 29467755, 2018). "In line with this, in subjects with multiple STH infections, associated with a higher infection intensity, treatment resulted in more pronounced effects, namely a significant reduction in adiponectin level, a trend for increase in leptin level, as well as a significant increase in L/A ratio." (PMID 29035384, 2017). "For example, infection with Taenia taeniaeformis is associated with lower levels of leptin." (PMID 24400300, 2013). "Since leptin is important for cell mediated immunity, low leptin concentrations during active TB may contribute to increased infection susceptibility, disease severity, and recovery with sequelae lesions." (PMID 21040518, 2010). "Hypoleptinemia resulting from depletion of white adipose may also increase the risk of death from infection through loss of immune competence, as leptin promotes T cell development, proliferation, and function and regulates many aspects of innate and acquired immunity." (PMID 40944251, 2025). "Importantly, the development of antibodies that could cross-react with endogenous leptin and cause an effective leptin-deficient state responsible for the loss of efficacy and infection has become a significant concern." (PMID 29910742, 2018). "Low serum leptin levels in BSCL patients could predispose to infections." (PMID 29883474, 2018). "Since nutritional deprivation increases the susceptibility to infection and associates with the amelioration of clinical manifestations of inflammation and autoimmunity, it will be important to address how this condition relates to the influence of leptin on both Teff and Tregs." (PMID 25601869, 2014). "However, serum leptin levels are reduced in infected children who are severely malnourished; therefore, diminished leptin concentrations in malnourished children may be involved in immune system dysfunction and increased susceptibility to infections." (PMID 21695035, 2011).
infection (continued). "The infection induces inflammatory responses in gastric cells responsible for leptin and ghrelin production." (PMID 40606632, 2025). "Collectively, these findings suggest that white adipose tissue reserves and leptin play critical roles in the defense against life-threatening infections." (PMID 40944251, 2025). "Parasitic infections can increase or decrease leptin levels depending on the type of parasite and the host’s immune response." (PMID 40864120, 2025). "Leptin is generally increased in the setting of infection and inflammation, and the leptin receptor (Ob-R) has shown the ability to activate the JAK-STAT, PI3K, and MAPK signaling pathways by acting similarly to IL-6 receptors." (PMID 41463203, 2025). "For example, during Leishmania donovani, T. cruzi, Mycobacterium tuberculosis and Pneumococcal pneumonia infections, elevated leptin is beneficial for improving the immune response, clearing pathogens and resolving infection." (PMID 39428707, 2025). "LEPR expression was specifically downregulated using siRNA treatment for 48h, then the recombinant human leptin (rLep) was added at 10 ng/mL (normal condition), and 100 ng/mL (hyperleptinemia) for 24 hours before infection." (PMID 40125513, 2025). "We measured serum levels of cytokines in control ob/ob mice (ob-ctrl) and mice supplemented with 75 ng/h leptin (ob-leptin) after infection." (PMID 39480494, 2024). "The visceral AT of mice infected with the Brazil strain of T. cruzi shows elevated levels of TNF, IFN-γ and IL-1, as well as reduced adiponectin and leptin, as a reflection of the inflammatory profile of the infection." (PMID 38533504, 2024). "In mammals, elevated plasma levels of GDF-15 or leptin have independent roles in appetite suppression and energy homeostasis and can modulate host response to pathogen infection." (PMID 37928534, 2023). "The increase of leptin levels during infection or inflammation indicates the importance of leptin on the host’s response to inflammation." (PMID 37155466, 2023). "Accumulating evidence showed that there was a change in the circulating level of leptin and adiponectin during infection with the intestinal helminth parasites." (PMID 37635188, 2023). "We also measured the impact of the infection on metabolic parameters, such as adiponectin and leptin, predominant cytokines produced by AT, and insulin as AT dysfunction has also been associated to the insulin pathway." (PMID 35661814, 2022). "Our results confirm that there is a very different response in many inflammatory genes transcripts after infection in a zebrafish leptin mutant." (PMID 35933481, 2022). "By applying either a p value or a FC filter, nine metabolites were changed following the same pattern in zebrafish larvae and mice in response to infection in the leptin mutant and WT." (PMID 35933481, 2022). "Several studies have found a beneficial effect (decreased severity and cytokine production) of leptin administration in murine models of infection." (PMID 35011102, 2022). "Leptin levels during infection and inflammation designates that leptin has role in the host defense mechanisms and immuneresponse." (PMID 37168792, 2022). "Regarding systemic leptin levels during infection with IAV, findings are quite variable, including both reports of upregulation of leptin in lean mice only and of constant leptin levels during infection." (PMID 33810619, 2021). "The role of leptin in the immune system response to infections has been investigated mostly working on mice models." (PMID 33804765, 2021). "Alti and colleagues presented the intervention of leptin in infections and they proposed leptin as an adjuvant tool in the development of new vaccines." (PMID 33907162, 2021). "In our work, we corroborated a decrease in leptin level and secretion with an increase body temperature in response to infection, thus excluding a positive role of leptin in biological response." (PMID 34437647, 2021).
infection (continued). "Nevertheless, the ob/ob mouse model helps to analyze the function of leptin in reactions to infection of the lung." (PMID 33810619, 2021). "Before the initial infection after the high-fat diet, similarly increased levels of triglycerides, cholesterol, leptin, or IL-6 have been detected." (PMID 33810619, 2021). "Overall, it appears that leptin primarily acts as a chemoattractant for neutrophils, particularly during infection in the lung." (PMID 33584724, 2020). "Overall, our work shows that N. caninum infection influences leptin production and leptin receptor expression early on in infection." (PMID 32709166, 2020). "In a previous work, we observed increased serum levels of leptin 21 days and 2 months after infection in wild-type C57BL/6 mice." (PMID 32709166, 2020). "Here, we found that earlier after infection, leptin levels were decreased in the serum of N. caninum-infected mice." (PMID 32709166, 2020). "Many studies have examined the effect of leptin treatment on various bacterial models of infection in mice." (PMID 33584724, 2020). "Our results show that acute infection with N. caninum led to a decrease in the levels of leptin that was also accompanied by decreased leptin receptor expression in adipose tissue." (PMID 32709166, 2020). "More specifically, a transient increase in the leptin level during acute inflammation can have a short-term benefit by helping leukocytes and other cell types during infection and tissue repair." (PMID 32824322, 2020). "Leptin (which secretion is enhanced in the SCAT upon infection) and insulin (which blood level is increased in infected mice) have been reported to promote WAT browning." (PMID 32409640, 2020). "Our results show that acute infection with N. caninum led to decreased leptin serum levels and mRNA expression in adipose tissue." (PMID 32709166, 2020). "Overall, our results show that N. caninum infection also influences leptin production during acute infection." (PMID 32709166, 2020). "It is possible that this increase in leptin can then stimulate the inflammatory response necessary to fight the infection that LPS is modeling." (PMID 33584724, 2020). "In acute inflammation and infection, leptin levels increase due to the presence of bacterial endotoxins and other signaling cytokines like TNF-a, IL-6, and IL-1b." (PMID 31186010, 2019). "In the condition of infection and immunity, serum leptin levels in the peripheral blood significantly increase." (PMID 29620639, 2018). "Leptin is known to be important for a proper response to infections and immunological homeostasis, but little is known about the in vivo modulation of neutrophil migration by leptin." (PMID 29467755, 2018). "At 12–72 h after infection with E. coli, the leptin content was significantly increased (p < 0.05) in the E. coli-infected groups compared with the uninfected groups." (PMID 30250258, 2018). "Investigations have shown that leptin is increased during acute infection and inflammation, indicating that leptin acts as a pro‐inflammatory cytokine." (PMID 28244652, 2017). "Leptin concentrations were 864.9 ± 191.0 pg/mL versus 560.7 ± 86.0 pg/mL at day 2 after infection and 1138.6 ± 446.1 pg/mL versus 682.6 ± 96.3 pg/mL at day 3 after infection (p = 0.029 in two-way ANOVA)." (PMID 28428684, 2017). "Leptin signal sensitivity was significantly altered after leptin vectors infection as represented by the change of phosphorylation of JAK2 and STAT3." (PMID 29250056, 2017). "Percentages of IFNγ-producing CD4+ and CD8+ T cells were significantly higher in leptin-treated infected mice compared with untreated infected mice after 60 days of infection." (PMID 27114296, 2016). "The increase in leptin production that occurs during inflammation and infection suggests that leptin part of the cytokine cascade." (PMID 28076486, 2016).
infection (continued). "Leptin production is increased during infection and inflammation, up-regulating both phagocytosis and the production of pro-inflammatory cytokines of the acute-phase response." (PMID 25662559, 2015). "In terms of infectious disease, the general consensus seems to be that leptin has an anti-inflammatory role, while at the same time serving a protective capacity against infections." (PMID 26184280, 2015). "The increase of the leptin levels during infection/inflammation suggests that it is a significant factor involved in the host's response to inflammation." (PMID 26697061, 2015). "Leptin was also found to be an important predictor of infection intensity, but the positive direction of the effect was unexpected." (PMID 26380705, 2015). "VHSV significantly up-regulated the transcription levels of both leptin and its receptor at day 5 post-infection." (PMID 25333488, 2014). "A prospective study was carried out in 61 patients with S. aureus bloodstream infection and circulating levels of IL-6, GRO-γ, RANTES and leptin were assessed over the course of the infection." (PMID 25398383, 2014). "The results showed that both infections increased the production of cortisol and decreased the production of leptin in the plasma compared with mock group, but the altered magnitude between both infection groups was variant." (PMID 23251416, 2012). "For PV-1, at the concentrations of 0.025, 0.05, 0.1 and 0.2 mg/ml, LeP inhibited viral replication by 11.2, 21.0, 23.6 and 63.8%, respectively, at time 0 h of infection." (PMID 22336004, 2012). "The AqE and LeP were more effective when added at 0 h of infection, however, EtOHE was more effective at the times 1 h and 2 h of the infection." (PMID 22336004, 2012). "Data obtained in human studies regarding the regulation of leptin expression in response to infection and inflammation are varied." (PMID 17641728, 2007). "Previous human studies have reported the association of low adiponectin levels or a decreased ALR with severe acute COVID-19 disease and mortality, but ours is the first study, to our knowledge, that analyzed the time course of adiponectin and leptin levels after the acute phase of infection." (PMID 40027795, 2025). "White adipose tissue also secretes leptin, which facilitates the immune response and may protect against mortality from infection." (PMID 40944251, 2025). "Chronic inflammation, whether due to infection or autoimmune disease, can lead to leptin resistance, particularly in the hypothalamus." (PMID 40095902, 2025). "In this context, elevated leptin during infection may contribute to adipocyte remodeling, promoting both cellular hypertrophy and hyperplasia." (PMID 40864120, 2025). "Moreover, an increase in leptin production during infection and inflammation has been previously demonstrated suggesting that this hormone is a part of the cytokine network which governs the inflammatory-immune response and defense mechanisms." (PMID 40959844, 2025). "Another potential mechanism that could explain the effect of T. gondii infection on thyroid gland hormones is that the infection could result in higher leptin hormone secretion." (PMID 39853582, 2025). "Additionally, HAdV-D36 infection can increase appetite in infected individuals by reducing the levels of norepinephrine and leptin, both of which are responsible for regulating satiety and hunger." (PMID 40941322, 2025). "In addition, the levels of one biomarker, leptin, were lower in the post-infection compared to pre-infection specimens at Visit 3, although by Visit 4 leptin returned to pre-infection levels." (PMID 38976697, 2024). "Overall, the results suggest that the beginning of SARS-CoV-2-induced infection is associated with lower serum levels of visfatin and its return to normal on the seventh day of infection but not with significant changes in leptin levels." (PMID 39200926, 2024).